IL6 (interleukin 6)
Diseases named in the same sentence as IL6 in open-access papers (continued):
Sharing a sentence is not in itself a finding about the gene and the disease.
breast cancer (continued). "In the present work, we have studied the specific contribution of the pro-inflammatory cytokines IL6 and IL8 in the acquisition of a tumorigenic phenotype using the well-characterized luminal breast cancer cell line MCF-7, which does not express IL6 or IL8 constitutively." (PMID 28472950, 2017). "Since we observed no significant changes in IL-6 transcription in IRE1 knockdown macrophages and no overall effect on macrophage-mediated breast cancer cell killing, our data suggest that these effects may be independent of TLR activation." (PMID 29113324, 2017). "Thus, the effect of IL-1β on TG2-overexpressing luminal-type breast cancer cells, which do not normally express TG2 or IL-6, was evaluated." (PMID 27609180, 2016). "Interleukin-6 (IL-6) enhances the survival of cancer stem cells (CSC) in several tumors including glioma and breast cancer, and increases the conversion of non-cancer stem cells into cancer stem cells in breast cancer models." (PMID 26287605, 2015). "Current evidence suggests that inflammatory cytokines, TNFα and IL-6, increase STS activity, although this has been disputed by a study showing negative correlation between TNFα/IL-6 expression and STS expression in soft tissue breast cancer metastases and primary tumors." (PMID 26213785, 2015). "Fatigue in breast cancer survivors has also been shown to correlate positively with peripheral CRP levels and leukocyte counts but not with IL1-receptor antagonist (RA), IL-6, and soluble TNF-Receptor1 (sTNF-R1), which again diminishes the role of a cytokine-specific mechanism." (PMID 25954147, 2015). "Similarly, ex vivo production of interleukin-6 (IL-6) and tumor necrosis factor-alpha (TNF-α) by lipopolysaccharide (LPS) stimulated monocytes was higher among fatigued compared to non-fatigued breast cancer survivors." (PMID 26247972, 2015). "One of the limitations of this report is that cytokines such as IL-6, IL-8, IL-1, and VEGF which are secreted by breast cancer cells were not determined and may contribute to the effects of PTHrP on bone resorption." (PMID 24959365, 2014). "The breast cancer cell lines, MCF-7 and MDA-MB-468, showed little or no response to IL-6, with an apparent dose-dependent increase in outliers, indicating that a small subset of the cells respond to IL-6 to the same extent as Cal33 or 686LN cells and with the same sensitivity as Cal33 cells." (PMID 25036749, 2014). "IL-6, a cytokine secreted by malignant cells and by nontumor cells in the surrounding tissues, activates STAT3 signaling, broadly characterized as a regulator of tumorigenesis, in mammary cancer cells and consequently weakens cell-to-cell adhesion, enhances motility and promotes the EMT." (PMID 38473317, 2024). "Considering that the IL6/IL6R/GP130 signaling pathway is important in tumorigenesis and metastasis, bazedoxifene is thought to have an antitumor effect, which has been proven preliminarily in breast cancer and pancreatic cancer but has not yet been studied in non–small cell lung cancer (NSCLC)." (PMID 39152779, 2024). "Since the pro-inflammatory cytokines IL-6 and IL-8 are consistently present in the SASP, and secreted by highly aggressive breast cancer cell lines, we aimed at elucidating their role on the less aggressive breast cancer cell line MCF-7, which does not secret these cytokines." (PMID 28472950, 2017). "Intrigued by our finding that SRF, which is essential for YAP-induced MaSC-like properties, is highly expressed in BLBC but not in luminal-type breast cancer, we investigated the possibility that YAP might activate IL6 expression and MaSC-like properties specifically in BLBC." (PMID 26671411, 2015). "However, in the breast cancer cells over-expressing ETV7, we could not observe this regulatory mechanism, even when STAT3 was activated by the treatment with IL-6, thus demonstrating that there is a putative competitive relationship between ETV7 and STAT3 in the regulation of the TNFRSF1A gene." (PMID 37041130, 2023).
breast cancer (continued). "Similarly, other subtypes of breast cancer cell lines including MCF-7 (luminal type), and MDA-MB-231 (basal type) also showed a decrease of E-cadherin and an increase of N-cadherin with Vimentin with IL-6 exposure while S-HBCC (cancer stem cell type) was not showed significant change." (PMID 33659239, 2020).
colitis (1,889 papers, 2007 to 2026). Inflammation of the colon. "Prophylactic N5 administration alleviated colitis symptoms (weight loss, colon shortening), reduced fecal and serum lipocalin-2 levels, and suppressed colonic pro-inflammatory cytokines (IL-1β, IL-6)." (PMID 40813467, 2025). "In this study, DSS-induced colitis in mice was associated with significant upregulation of IL-6, TNF-α, and IL-1β." (PMID 41257293, 2025). "Triptolide has been shown to alleviate colitis in IL-10-deficient mice by inhibiting the IL-6/STAT3 and IL-17 signaling pathways." (PMID 41476955, 2025). "Paradoxically, NF-κB signaling in CAFs has dual regulatory roles: IKKβ activation suppresses hepatocyte growth factor (HGF)-mediated intestinal tumorigenesis via SMAD7 and SMURF1 induction but promotes colitis-associated cancer through IL-6 overproduction." (PMID 40562870, 2025). "In colorectal cancer, MARCHF inhibits the activation of the IL-6 signaling pathway by ubiquitinating and degrading the IL-6 receptor, thereby attenuating the development of colitis and inflammation-associated tumor progression." (PMID 40225866, 2025). "Galectin 4 (Gal-4) is associated with an increase in the pro-inflammatory interleukin 6 (IL-6) during colitis, while Galectin 9 (Gal-9) is associated with an increase in the anti-inflammatory role during EAE by favoring the apoptosis of Th1 cells." (PMID 40650248, 2025). "Mice treated with fucoidan exhibited significant protection from colitis, evidenced by longer colonic length, less weight loss, and lower expression levels of inflammatory genes such as Il‐1b, Il‐18, Il‐6, Nos2, and Tnfα." (PMID 40545965, 2025). "Inflammatory cytokines, such as TNF-α, IL-1β, and IL-6, are central mediators of the mucosal immune response and are closely linked to the pathogenesis of colitis-stimulated inflammation." (PMID 41614862, 2025). "AhR activation has been linked to the alleviation of colitis by reducing inflammatory cytokines like IL‐1β, IL‐6, and TNF‐α, while enhancing anti‐inflammatory cytokines, such as IL‐4, IL‐10, and IL‐22, and strengthening the intestinal epithelial barrier." (PMID 39836604, 2025). "Specifically, the plant’s ability to fight colitis was linked to higher IL-10, lower IL-6, and lower TNF-α levels." (PMID 40822453, 2025). "IL-6 is associated with the development of intestinal diseases such as colorectal cancer and colitis." (PMID 40431255, 2025). "The administration of this cheese to mice with TNBS-induced colitis significantly prevented weight loss and reduced disease scores and the inflammation marker IL-6 in blood." (PMID 40563526, 2025). "IL-6 has been shown to play a key role in experimental colitis, and its high levels are a substantial risk factor for colon cancer and hepatocellular carcinoma in humans." (PMID 39474054, 2024). "In vivo, strains of B. dentium were able to relieve colitis symptoms in a DSS stimulated mice model, decreased weight loss and levels of TNF, IL-8 and IL-6 inflammatory markers in a TNBS-induced colitis mice model." (PMID 38951788, 2024). "Animal models have shown that IL-6 enhances tumor growth associated with colitis, and this effect can be inhibited by blocking IL-6." (PMID 38867310, 2024). "An upsurge in the pro-inflammatory cytokines such as IL-6 and IL-1β in the colitis condition has been linked with chronic colitis." (PMID 37695333, 2024). "This markedly elevates the mRNA levels of NR4A2, COX2, and the regulatory proteins AREG and IL-6, thereby facilitating the development of sporadic or colitis-associated colon cancer." (PMID 39683442, 2024). "HT ameliorated DSS-induced colitis in mice, showing marked improvement in weight loss, colon length, colonic pathological severity, and the levels of TNFα and IL6 in serum." (PMID 39064786, 2024). "In a previous study, IL-6 deficiency promoted the development of colitis by recruiting more neutrophils, which secreted MPO and destroyed the intestinal epithelium." (PMID 39275347, 2024).
colitis (continued). "TET2 inactivation has been considered to underlie the proinflammatory milieu, as Tet2 knockout mice are susceptible to DSS-induced colitis with hyperactivation of Il6 during inflammation." (PMID 38822028, 2024). "IL-6: The progression of colitis-associated colorectal cancer was also significantly affected by IL-6." (PMID 38717677, 2024). "DSS-induced colitis model animals have been reported to have elevated levels of several proinflammatory cytokines, including IL-6 and IL-11, both of which are associated with CRC development via p-STAT3." (PMID 38504172, 2024). "To this end, we analyzed the main pro-inflammatory cytokines associated with DSS-induced colitis, such TNFα, IL-1β, IL-12p40, and IL-6, at the transcription level." (PMID 39456254, 2024). "The development of colitis has been directly associated with inflammatory cytokines, such as IL‐6, IL‐17, TNF‐α, and interleukin 23 (IL‐23)." (PMID 39723032, 2024). "The regional delivery of CNP-miR146a improved weight loss and decreased colon inflammation in mice in this model, as seen on histology and through the downregulation and normalization of proinflammatory cytokines IL-6 and TNF." (PMID 38786849, 2024). "In the pathogenesis of colitis, IL-6 and IL-22 are inflammation-associated markers that correlate with the activation of the JAK and STAT3 pathways." (PMID 39133435, 2024). "The chemokine CCL5, which stimulates inflammation and epithelial cell proliferation through the IL-6 pathway, is expressed by the microbiota and is linked to both colitis and colitis-associated carcinogenesis." (PMID 38248332, 2024). "Inflammatory cytokines including IL-1β, TNF-α, and IL-6 are linked with effects of the fecal microbiome on ICI colitis; IL-6 also drives irAEs in other organs." (PMID 36622383, 2023). "In mouse models of colitis-associated colon cancer, PPARβ/δ increased IL-6 expression and phosphorylation of STAT3, promoting tumorigenesis, while the concomitant 15-lipoxygenase-1 in colon epithelial cells inhibited these effects by downregulating PPARβ/δ." (PMID 37251321, 2023). "sakei K040706 isolated from soybean paste has been reported to inhibit pro-inflammatory factors such as nitric oxide (NO), TNF-α, IL-1β, and IL-6 and reduce inflammatory cell infiltration, thereby weakening the severity of colitis caused by DSS in mice." (PMID 36766113, 2023). "For the clinical application of ADS024 in UC, it was shown that oral live ADS024 bacterial treatment successfully ameliorated DSS colitis in mice and with reduced weight loss, disease activity, mucosal injury, and colonic IL-6 and TNFα expression." (PMID 38268707, 2023). "Previous studies about the interference of Slc11a1 polymorphism in DSS-induced colitis pointed out the role of IL6 and IFNγ in this disease." (PMID 36792680, 2023). "Studies have indicated that in patients undergoing ICI (immune checkpoint inhibitor) therapy for malignant melanoma, a lower baseline level of IL-6 is strongly linked to the development of immune-related adverse events such as colitis." (PMID 37895833, 2023). "The characterization of the IL-6/GMDS-AS1/HuR/STAT3 axis provides a new perspective for understanding the pathogenesis of colitis-associated CRC and a novel diagnostic and therapeutic target in CRC." (PMID 36849492, 2023). "STAT3 activation induced by IL-6 is critical in colitis-associated CRC growth and is known as the main mediator of EMT induction." (PMID 37047623, 2023). "In this review, we concluded that anti-BMP6 reagents, exogenous BMP7 and FST all have impacts on decreasing IBD-associated pro-inflammatory cytokines, especially IL-6 which attenuates DSS-induced mice colitis." (PMID 37391444, 2023). "IL-6, which was mainly investigated in this study, was previously found to be elevated in the progression of CRC, and an IL-6 signaling blockade in a colitis-associated CRC murine model revealed a decreased tumor burden." (PMID 37047623, 2023).
colitis (continued). "The elevated levels of IL-6 and IL-10 are also linked with dermatological irAEs, while lower levels of IL-6 are reportedly associated with colitis." (PMID 35774996, 2022). "Enriched A. muciniphila eroded the mucus layer, impairing the intestinal barrier, which in turn posed greater susceptibility to colitis in mice, and induced excessive secretion of inflammatory cytokines (IL-1β, IL-6, and TNF-α)." (PMID 36312913, 2022). "We here demonstrate that acute colitis causes loss of body weight, colon shortening, intestinal damage and high levels of inflammation with elevated local levels of Il-6 and iNOS, as well as microglia activation in the colon." (PMID 36232813, 2022). "Conversely, lower levels of circulating IL-6 at baseline were associated with a higher likelihood of developing irAEs, particularly colitis, in patients with melanoma that were treated with ipilimumab." (PMID 35565190, 2022). "G significantly ameliorated the extent of colitis, which was associated with a decrease in the expression levels of pro-inflammatory cytokines and chemokines, including interleukin IL-1β, IL-6, TNF-α, CXCL2, and CCL2 in the inflamed mucosa." (PMID 35456938, 2022). "In colitis-associated colorectal cancer, IL-6 was identified as a critical tumour-promoter during early tumorigenesis by protecting pre-malignant intestinal epithelial cells from apoptosis." (PMID 35326545, 2022). "On the other hand, activation of mTOR signaling can cause colitis, and overproduction of IL-6 can inhibit Treg proliferation." (PMID 35237152, 2022). "IL‐6 is a prototypical protumorigenic cytokine that contributes to the initiation and progression of colitis‐associated tumorigenesis by promoting cell progression, survival, tumour invasion and metastasis." (PMID 35363937, 2022). "Previous studies have shown that DSS-induced colitis caused cortical inflammation, as demonstrated by significant elevation of proinflammation cytokines (il-6 and tnf-α) and increased microglial activation in cortical tissue." (PMID 36776388, 2022). "As TNF, IL-6 is also involved in the inflammatory process related to colitis and is associated with the regulation of the adaptive immune response." (PMID 35295931, 2022). "GNAI3 is a potential tumor suppressor, which inhibits GNAI2-mediated myeloid-derived suppressor cells (MDSCs) proliferation and Colitis-Associated tumorigenesis by negatively regulating IL6 signaling pathway." (PMID 36042374, 2022). "In mice with dextran sulfate sodium (DSS)-induced colitis, Reg3γ protein expression was upregulated and the STAT3-associated cytokines (such as IL-6, IL-17, and IL-22)/Reg3γ axis played a pivotal role in the acute phase of colitis." (PMID 34811636, 2022). "We measured the levels of inflammatory cytokines such as IL-1β, TNF-α, IL-6, and IL-10, which are linked to colitis." (PMID 36456585, 2022). "The differences in colitis corresponded with markedly reduced colonic expression of genes encoding the proinflammatory molecules IL-6 and Lcn2 in the CTB-Ent group compared to CTB control mice." (PMID 36094114, 2022). "Cytokines associated with colitis inflammation (IL-1β, IL-6, and IL-17A) are significantly inhibited after treatment with M2b macrophage exosomes." (PMID 34683937, 2021). "IL-6 has also been demonstrated to induce MDSC expansion in the process of colitis-associated tumorigenesis and enhance the immunosuppressive function." (PMID 34689842, 2021). "After treatment with HMC, colitis improvement was associated with the rise in colon antioxidant status and the inhibition of pro-inflammatory cytokines IL-1β, IL-6, IL-33, and TNF-α in the colon." (PMID 33499333, 2021). "Contrarily, IL6 is a proinflammatory cytokine with higher severity of colitis being associated with increased IL6 expression." (PMID 35008767, 2021). "In vagotomized mice a more severe form of inflammation developed after DSS-induced colitis, which was associated with increased levels of IL-1β, IL6, TNFα, and NF-κB levels." (PMID 33562721, 2021).